EDN1 (endothelin 1)
Diseases named in the same sentence as EDN1 in open-access papers (continued):
Sharing a sentence is not in itself a finding about the gene and the disease.
Insulin resistance (continued). "This, partly because insulin resistance impairs the production of NO, favors the production of endothelin-1 and the vasoconstrictive and mitogenic responses on the vascular wall." (PMID 23573411, 2013). "Previous studies have revealed that endothelin-1 induces insulin resistance by suppressing glucose uptake and lipolysis in adipocytes through ETA receptors." (PMID 22748184, 2012). "It is GRK2 which mediates endothelin-1-induced insulin resistance via the inhibition of both Gαq/11 and insulin receptor substrate-1 pathways in these cells." (PMID 20204079, 2009). "Of interest here is the finding that GRK2 mediates endothelin-1-induced insulin resistance via the inhibition of both Gαq/11 and insulin receptor substrate-1 pathways in 3T3-L1 adipocytes." (PMID 20204079, 2009). "Mechanistically, angiotensin II and endothelin-1 directly inhibited insulin receptor substrate-1 phosphorylation, promoting systemic insulin resistance, while hyperinsulinemia stimulated vascular smooth muscle cell proliferation and endothelin-1 secretion, further increasing vascular resistance." (PMID 40022080, 2025). "However, in a context of endothelial insulin resistance, there is a selective decrease in insulin-mediated effects on the PI3K-AKT-eNOS pathway, causing an imbalance between NO and endothelin-1 production." (PMID 41373661, 2025). "The administration of endothelin-1 (ET-1), a vasoconstrictor, leads to insulin resistance, as characterized by a decrease in IRS-1 protein levels and suppressed PI3K/Akt activation in rat skeletal muscle and adipocytes, further promoting increased vasoconstriction and atherogenesis." (PMID 33937238, 2021). "Third, insulin resistance can increase the vessel tone by activating endothelin-1 and angiotensin II type 1 receptors, and the Atherosclerosis Risk in Communities Study reported that insulin resistance was associated with arterial stiffness in patients with type 2 DM." (PMID 33036608, 2020). "A possible explanation is an impaired insulin signaling through PI3K signaling pathway and the increased vascular inflammation noted in insulin resistance which can decrease nitric oxide (NO) production and increase Endothelin-1 (ET-1) secretion leading to raised blood pressure." (PMID 27597980, 2016). "Circulating endothelin-1 levels were associated with both insulin resistance (HOMA-IR) and apoB/apoA1 ratio in men whereas no such associations were observed in women." (PMID 26573599, 2015). "This links directly endothelin-1 with insulin resistance and obesity." (PMID 23573411, 2013). "Furthermore endothelial function is impaired in insulin resistance through imbalance of nitric oxide production and the release of vasoconstrictor endothelin-1." (PMID 22098712, 2011). "Moreover, plasma endothelin-1 level is positively correlated with insulin resistance in humans." (PMID 39518432, 2024). "However, several animal studies have demonstrated that high endothelin-1 but low adrenomedullin were involved in the development of insulin resistance, suggesting that both vasoactive peptides may be associated with changes in glucose metabolism." (PMID 33066780, 2020). "Similarly, a research in endothelin-1 (ET-1) has emphasized the use of ET-1 treatment resulted in heterologous desensitization of insulin signalling, defined as chronic ET-1-induced cellular insulin resistance." (PMID 30621321, 2019). "Insulin resistance induces an impairment in phosphatidylinositol 3-kinase (PI3K) – dependent signaling, which in endothelium may cause imbalance between production of nitric oxide and secretion of endothelin-1, leading to endothelial dysfunction." (PMID 18416854, 2008). "Intermittent hypoxia and insulin resistance in OSAHS patients can promote the increase of inflammatory markers, including nitric oxide (NO), endothelin-1(ET-1), interleukin-6 (IL-6), and C-reactive protein (CRP)." (PMID 33628835, 2021).
Insulin resistance (continued). "↑ BW (decreased in T1DM model); ↓ BW, plasma insulin levels, insulin resistance (increased in T2DM model) and ↓ s-glu, HbA1c, albuminuria, s-creat, oxidative stress, HO-1, NF-κB, mesangial expansion, ECM, fibronectin, collagen 4-α1, VEGF, endothelin-1, and TGF-β1." (PMID 39652245, 2024).
glaucoma (85 papers, 2008 to 2025). Increased pressure in the eyeball due to obstruction of the outflow of aqueous humor. "One of the key factors implicated in the pathogenesis of glaucoma is endothelin-1 (ET-1), a 21-amino-acid vasoactive peptide belonging to the endothelin family." (PMID 39684751, 2024). "Reduced expression of AQP1 is believed to be responsible for increased resistance to aqueous humor outflow that leads to elevated IOP in glaucoma associated with increased endothelin-1 (ET-1) level in aqueous humor." (PMID 35346303, 2022). "As well as perturbations in the endothelin-1 pathway, there is also longstanding evidence that impaired NO signaling is implicated in glaucoma." (PMID 32656207, 2020). "EDN1 is elevated in aqueous humor of some glaucoma patients and EDN1 has been shown to cause retinal ganglion cell death in experimental models for glaucoma." (PMID 27930693, 2016). "The purpose of this study was to ascertain whether a correlation exists between glaucoma-associated alteration of ocular vascular haemodynamics and endothelin-1 (ET-1) levels exist." (PMID 35821224, 2022). "Therefore, NO and endothelin-1 are associated with IOP elevation in glaucoma through a decrease in NO production or an excessive increase in endothelin-1 secretion." (PMID 31055889, 2019). "Several studies have suggested a relationship between elevated plasma levels of endothelin-1 (ET-1) and glaucoma progression." (PMID 41154592, 2025). "Aberrant endothelin-1 (ET-1) levels in aqueous humor have been reported across a variety of vascular diseases of the eye, including glaucoma." (PMID 39856599, 2025). "Endothelin-1 (ET-1), a potent vasoactive peptide, has been shown to produce neurodegenerative effects in animal models of glaucoma." (PMID 39684751, 2024). "Background and Objectives: Several studies suggest the complex relationship between Endothelin-1 (ET-1) levels with various types of glaucoma." (PMID 39064546, 2024). "The authors of the study were able to detect the expression of TUBB3 in desmin-, PDGFR-β- and α-SMA-positive pericytes, as well as in endothelin-1-positive endothelial cells in eyes affected by glaucoma." (PMID 39318470, 2024). "Central among these mediators is endothelin-1 (ET-1), a potent vasoconstrictive peptide, which is elevated in aqueous and plasma concentrations of glaucoma patients." (PMID 38132117, 2023). "In glaucoma, endothelin-1 (ET-1)-induced ROCK signaling plays a role in regulating retinal blood flow and vasomotor tone, resulting in the promotion of vasoconstriction." (PMID 37959203, 2023). "Caspase 3 activation in RGCs and later RGC loss after EDN1 exposure was dependent upon JUN activation, similar to RGC death after glaucoma-relevant injuries including optic nerve crush and ocular hypertension." (PMID 35429992, 2022). "TM contractility is induced by endothelin 1 (EDN1), a potent vasoactive peptide, which has been linked to glaucoma pathogenesis in both humans and animal models." (PMID 35689009, 2022). "In the rabbit model of glaucoma, administration of endothelin-1 to the anterior optic nerve region induced a significant decrease in local blood flow." (PMID 33919241, 2021). "Endothelin-1 (ET-1) is a vasoactive peptide that is elevated in aqueous humor as well as circulation of primary open angle glaucoma (POAG) patients." (PMID 32107448, 2020). "Future work should elucidate the role of EDNRA and hypoxia in mediating RGC death after EDN1 insult and in models of glaucoma." (PMID 32980857, 2020). "Most usually, the level of circulating endothelin-1 (ET-1) was increased in patients who suffer from glaucoma." (PMID 31949441, 2019). "Endothelin-1 (ET-1) is suggested to be involved in the impairment of ONH blood flow observed in glaucoma eyes." (PMID 29236784, 2017). "Plasma endothelin-1 (ET-1), a very potent vasoconstrictor produced mainly by vascular endothelial cells, has been found to be increased in glaucoma patients." (PMID 27649414, 2016).
glaucoma (continued). "Many reports confirm that endothelin-1 has its part in the pathogenesis of glaucoma by influencing local blood flow in the eyeball, as well as regulating intraocular pressure and retinal ganglion cell apoptosis." (PMID 26697209, 2015). "Paradoxically, or perhaps in response to the breakdown of the blood–retinal barrier, reactive ONH astrocytes have also been found to express increased levels of endothelin-1 (ET-1) receptors in experimental glaucoma." (PMID 25490529, 2015). "Endothelin-1 values are higher in glaucoma patients, particularly normal-tension glaucoma patients who commonly suffer from a FS, compared to healthy controls." (PMID 25312339, 2014). "Endothelin 1 signaling is believed to be important in regulating retinal blood flow during an immune response, and is upregulated in mouse and rat models of glaucoma." (PMID 23687432, 2013). "A growing body of evidence suggests that endothelin-1 (ET-1), a 21 amino acid vasoactive peptide, is a contributor to the etiology of glaucoma and is one of the factors increased in response to elevated IOP." (PMID 24265756, 2013). "Corroborative evidence from several laboratories suggests that endothelin-1 (ET-1), a vasoactive peptide, has neurodegenerative effects in glaucoma." (PMID 22916224, 2012). "In addition, alteration of the tone of TM cells induced by various factors present in the aqueous humor such as TGFβ2, lysophosphatidic acid (LPA), and endothelin 1 (ET-1) have been hypothesized to contribute to the pathogenic increase in outflow resistance in glaucoma." (PMID 23272142, 2012). "Compromised availability of NO as well as an imbalance between NO and endothelin-1 [ET-1] have been reported in glaucoma patients." (PMID 24600624, 2012). "Endothelin-1 (ET-1), one of three endothelin isoforms, is the most potent vasoconstrictor in the human body and the most potent contributor to the pathophysiology and dysfunction of retinal BF in glaucoma." (PMID 40345829, 2025). "Patients with glaucoma suffer compromised endothelial cells (ECs) function and increased plasma and aqueous humor levels of endothelin-1 (ET-1), which could lead to NOX activation." (PMID 38649885, 2024). "Similar to models of glaucoma-relevant axonal injury and ocular hypertension, deletion of Jun from RGCs prevented caspase 3 activation in RGCs and prevented later RGC loss after intravitreal EDN1 injection." (PMID 35429992, 2022). "Chronic low-level hypoxia mediated by endothelin signaling may lead to compromise of the blood-brain barrier after EDN1 exposure and in glaucoma." (PMID 35429992, 2022). "It was found that patients with allergic rhinitis and glaucoma both had high levels of nitric oxide, which may accompany with increased endothelin-1 (ET-1) levels." (PMID 34828558, 2021). "Astroglial activation in glaucoma has been shown to increase the expression of many factors, including endothelin-1 (ET-1), tumor necrosis factor-α (TNF-α), oxidative stress molecules, and trophic factors, e.g., CNTF, with varied neuroprotective and harmful properties." (PMID 33796062, 2021). "Thus, in the present study, EDN1-induced cell death appeared to be specific to RGCs, similar to glaucoma pathology, and it remains possible that hypoxia plays a role in glaucomatous and EDN-induced RGC death." (PMID 32980857, 2020). "Of those, vascular endothelial dysfunction in glaucoma was demonstrated by reduced brachial artery flow-mediated vasodilation or exaggerated vasoconstriction of arteries dissected from gluteal fat biopsies in response to 5-hydroxytryptamine and endothelin-1." (PMID 28006020, 2016). "In addition, high levels of endothelin-1 (ET-1) have been observed in patients with normal tension glaucoma, open angle glaucoma, and animal models of glaucoma." (PMID 18836575, 2008).
glaucoma (continued). "In addition, we also explored whether CTSK is regulated by dexamethasone (DEX), TGFβ2, Endothelin 1 (Endo-1), and connective tissue growth factor (CTGF); each of which has been implicated in elevated IOP and glaucoma." (PMID 34831087, 2021). "Likewise, the endothelin-1 (ET-1) signalling was also significantly detected in this investigation and this protein signalling has been associated with the pathogenesis of glaucoma, regardless of the intraocular pressure." (PMID 27922054, 2016). "Various studies have shown that endothelin-1 (ET-1), a vasoactive peptide, acting through its G protein coupled receptors, ETA and ETB, plays a pathophysiologic role in glaucoma." (PMID 38464735, 2023). "Considering EDN insult caused activation of JUN in 30% of RGCs and 69% of cCASP3+ RGCs were also JUN+ after EDN1 insult, it remained possible that JUN regulates EDN1-induced RGC death, similar to glaucoma-relevant RGC death." (PMID 32980857, 2020). "The endothelin family of peptides and receptors, particularly endothelin-1 (ET-1) and endothelin B (ETB) receptor, has been shown to have neurodegenerative roles in glaucoma." (PMID 28249604, 2017). "Different retinal injuries upregulate both EDNRA and EDNRB, as well as EDN1 and EDN2, and a growing body of data suggests roles in retinal pathogenesis including diabetic retinopathy and glaucoma." (PMID 27930693, 2016). "Impaired endothelial cell function has been described in glaucoma patients, as well as increased blood plasma and aqueous humour levels of endothelin-1, although this finding is not specific to glaucoma patients alone." (PMID 33557289, 2021). "In our small sample of otherwise healthy glaucoma patients, increased concentrations of Endothelin-1 in the aqueous humor did not influence the surgical outcome of standard trabeculectomy with MMC during up to four years of follow-up." (PMID 26904271, 2016). "Endothelin-1 (ET-1) is a 21-amino acid vasoactive peptide that plays a key role in the pathogenesis of glaucoma; however, the receptors mediating these effects have not been defined." (PMID 22916224, 2012). "Regarding genetic glaucoma models, we considered the main hallmarks and limitations of DBA/2J, glutamate/aspartate transporter/excitatory amino acid carrier 1, myocilin, connective tissue growth factor, optineurin, purinergic receptor 2Y, caveolin 1, and endothelin-1 mice." (PMID 41227293, 2025).
Obesity (78 papers, 2010 to 2025). Accumulation of substantial excess body fat. "Elevated endothelin-1 activity also played an important role in obesity- associated endothelial dysfunction." (PMID 31575927, 2019). "This study first reported significant interactions of EDNRA and EDN1 polymorphisms with gender, regular exercise, and obesity on carotid IMT in Han Chinese participants." (PMID 26040574, 2015). "Genetic variants in the NOS1 and EDN1 genes appear to account for important components of the variance in endothelial function, particularly when concurrent risk factors such as obesity exist." (PMID 24063765, 2013). "Obesity was also associated with increased expressions of angiogenesis-related proteins, in particular, angiogenin, endoglin, endostatin, endothelin-1, IGFBP-3, leptin, MMP-3, PAI-1, TIMP-4, CXCL16, platelet factor 4, DPPIV and coagulation factor III." (PMID 22748184, 2012). "Moreover, endothelin-1 (ET-1), a potent vasoconstrictor, has been implicated in the pathophysiology of obesity, with increased levels in the blood and tissues associated with adverse metabolic outcomes." (PMID 38756259, 2024). "Understanding the mechanisms underlying the observed changes in adiponectin and endothelin-1 in response to exercise and diet will be crucial in developing targeted interventions for improving metabolic health and reducing the burden of obesity-related diseases." (PMID 38756259, 2024). "The aim of this study was to evaluate the interacted association between EDNRA and EDN1 polymorphisms and gender, regular exercise, and obesity status on carotid intima media thickness (IMT) in community- dwelling subjects of the Taichung Community Health Study." (PMID 26040574, 2015). "Still, further studies will be necessary to genotype other important variants underlying the EDNRA and EDN1 signals, and to elucidate the mechanisms with which gender, regular exercise, and obesity modify the effects of these polymorphisms on carotid IMT in Han Chinese." (PMID 26040574, 2015). "The observed changes in adiponectin and endothelin-1 levels following swimming stress in rats highlight the potential of exercise as a key component of integrated strategies for managing obesity and enhancing cardiovascular health." (PMID 38756259, 2024). "Studies conducted in adults have revealed that individuals with obesity exhibit higher levels of vasoconstrictor molecules such as endothelin-1, angiotensin-II, and various arachidonic acid metabolites." (PMID 37680774, 2023). "Since obesity is known to induce systemic inflammation and increase vascular endothelin-1 and endothelin-1 receptor expression, adipose tissue can function as a modulator of PH." (PMID 37240457, 2023). "Multiple vascular contractile agonists generate their responses by activating Rho-kinase pathway including endothelin-1, angiotensin-II, and arachidonic acid metabolites (thromboxane A2), in common, these important mediators are elevated in obesity." (PMID 37342890, 2023). "After multivariate adjustment, the effects of interactions between EDNRA and EDN1 gene with gender, obesity, and exercise were observed." (PMID 26040574, 2015). "In studies of experimental obesity, an increase in endothelin-1 gene and protein expression has been detected within the cardiovascular system." (PMID 23573411, 2013). "Endothelin-1 (ET1), another important regulator of vascular homeostasis, may also contribute to obesity-related cardiometabolic risk, with evidence suggesting sex-specific differences, including delayed onset in women." (PMID 40217594, 2025). "Plasma endothelin-1 levels are elevated in patients with obesity and type 2 diabetes, but the primary source of circulating endothelin-1 in these conditions is unknown." (PMID 37383400, 2023).